FABP5 (fatty acid binding protein 5)
Diseases named in the same sentence as FABP5 in open-access papers (continued):
Sharing a sentence is not in itself a finding about the gene and the disease.
esophageal squamous cell carcinoma (2 papers, 2021 to 2024). Esophageal squamous cell carcinoma (ESCC) is a type of esophageal carcinoma (EC) that can affect any part of the esophagus, but is usually located in the upper or middle third. "Considering that both are closely related to retinoic acid, CRABP2 and FABP5 are expected to be targets for predicting esophageal squamous cell carcinoma and clinical treatment." (PMID 34632074, 2021). "The purpose of this study was to explore the effect of CRABP2 and FABP5, and their ratio on prognosis in esophageal squamous cell carcinoma." (PMID 34632074, 2021).
Hypercholesterolemia (2 papers, 2023 to 2025). An increased concentration of cholesterol in the blood. "In response to d-flow under hypercholesterolemia, all MΦ clusters significantly accumulated, most notably MΦ3 and MΦ4 that highly expressed the markers of foam cells (Trem2, Lgals3, Gpnmb, Spp1, Lpl, and Fabp5)." (PMID 40092444, 2025). "Lastly, although we conducted immunohistochemical staining experiments in vivo to verify the role of Fabp5 in AP, the mechanisms underlying how hypercholesterolemia affects the expression of Fabp5 and how Fabp5 exacerbates the severity of AP have not been validated in vivo and in vitro." (PMID 38188879, 2023).
pancreatic ductal adenocarcinoma (2 papers, 2017 to 2023). An infiltrating adenocarcinoma that arises from the epithelial cells of the pancreas. "Previous studies have observed a correlation between the expression of CAFs and CRABP2 in pancreatic ductal adenocarcinoma (PDAC), where the two transporters of ATRA, fatty acid binding protein 5 (FABP5) and CRABP2, always appear in a high FABP5: CRABP2 ratio in quiescent fibroblasts." (PMID 38186580, 2023).
pancreatitis (2 papers, 2023 to 2024). Inflammation of the pancreas. "Reduced protein expression of Fabp5 has been observed in pancreatic stellate cells in diseased states such as pancreatitis and ductal adenocarcinomas when compared with healthy fibroblasts." (PMID 39000422, 2024). "Moreover, the immunohistochemical staining suggested that Fabp5 expression was markedly increased in pancreatic tissues of the experimental pancreatitis model." (PMID 38188879, 2023).
periodontitis (2 papers, 2019 to 2026). An acute or chronic inflammatory process that affects the tissues that surround and support the teeth. "On the other hand, FABP5 can regulate the production of prostaglandin E2 and S100A2 is associated with inflammatory processes such as periodontitis and constitutes a candidate for biomarker of inflammation in this context." (PMID 30648003, 2019).
prostate tumor (2 papers, 2018 to 2023). "As prostate tumors often develop taxane resistance, in this study we sought to ascertain the impact of FABP5 upon docetaxel resistance in a taxane-resistant PC cell-line harboring ABCB1 overexpression." (PMID 37796964, 2023). "Prior work from our group showed that small molecule inhibitors of FABP5 synergize with taxane therapeutics to reduce prostate tumor growth." (PMID 37796964, 2023). "Pharmacological or genetic inhibition of FABP5 dampens peroxisome proliferator-activated receptor gamma activation, reduces tumor growth, and attenuates the metastatic potential of prostate tumors." (PMID 37796964, 2023).
steatosis (2 papers, 2024 to 2025). Increased lipid within the cytoplasm of cells. "GalNAc‐siRNAs targeting hepatic FABP5 ameliorate hepatic steatosis." (PMID 40231957, 2025).
vitamin A deficiency (2 papers, 2020 to 2021). Deficiency of vitamin A due to malnutrition, malabsorption, or dietary lack. "Septoclasts in the present FABP5-deficiency mutant tibiae had shorter processes than those of WT control in a way similar to septoclasts in tibiae of vitamin A-deficiency mice, in which the activity of septoclasts to resorb cartilages is reduced." (PMID 33398436, 2021).
acne (1 paper, 2026). An inflammatory process of the sebaceous glands which is characterized by comedones, nodules, papules and/or pustules on the skin. "Altogether, these findings indicate that altered lipogenesis, retinoid signaling, and keratinocyte differentiation are key features of acne, and nominate AP-1 and FABP5 as potential therapeutic targets." (PMID 41657309, 2026).
acute pancreatitis (1 paper, 2023). An acute inflammatory process that leads to necrosis of the pancreatic parenchyma. "“Fabp5” gene was identified as the common differentially expressed gene between a high-cholesterol diet and acute pancreatitis." (PMID 38188879, 2023). "High-cholesterol diet may affect the severity of acute pancreatitis by regulating the expression of Fabp5, resulting in enhanced activation of TLR signaling and the Nuclear Factor-κB pathway." (PMID 38188879, 2023). "An artificial neural network (ANN) model consisting of Fabp5, TLR4, Actb and Cdh1 was useful in predicting severe acute pancreatitis." (PMID 38188879, 2023).
Adrenocortical carcinoma (1 paper, 2023). "FABP5 expression was associated with pathological stages of Adrenocortical carcinoma (ACC), BLCA, CESC and KIRC (ACC p = 0.011, BLCA p = 0.001, CESC p = 0.034 and KIRC p = 0.009)." (PMID 36906605, 2023).
aniridia (1 paper, 2026). Aniridia is a congenital ocular malformation characterized by the complete or partial absence of the iris. "Downregulation of fatty acid binding protein 5 (FABP5) has been reported in conjunctival cells of congenital aniridia patients and in limbal epithelial cells (LECs) of the PAX6 siRNA knockdown model." (PMID 42048350, 2026).
aortic aneurysm (1 paper, 2022). A ruptured aneurysm located in the wall of the proximal portion of the descending aorta proceeding from the arch of the aorta. "We identified a subpopulation of the Trem2 macrophage featured biological function on macrophage migration and expression of SPP1, TREM2, FABP5, and ANXA2 in both organisms during the pathology of aortic aneurysm." (PMID 36703732, 2022).
atopic march (1 paper, 2023). sequential manifestations of different allergic diseases such as eczema, asthma and rhinitis. "The expression of fatty-acid-binding protein 5 (FABP5) in the skin and T cells of individuals with atopic march and in murine models of atopic march showed a positive correlation with IL-17A levels in both the skin and serum." (PMID 38256282, 2023).
brain ischemia (1 paper, 2021). Diminished or absent blood supply to the brain caused by obstruction (thrombosis or embolism) of an artery resulting in neurologic damage. "In summary, the present study suggested that increased FABP3, FABP5 and FABP7 expression in the brain is a novel biochemical marker of cerebral ischemia and that the FABP inhibitor, MF6 inhibited their expression levels to play a neuroprotective role in cerebral I/R in mice." (PMID 34068550, 2021). "Furthermore, FABP5 inhibition reduces the nuclear transport of NF-κB, thereby decreasing mPGES-1 expression and PGE2 synthesis, NF-κB also induces the expression of various pro-inflammatory genes and induces neuronal death in cerebral ischemia." (PMID 34068550, 2021).
central obesity (1 paper, 2024). "Lipid synthesis-associated protein FABP5 was identified as a specific interacting protein of JMJD1C and binds to the jumonji domain of JMJD1C, suggesting its potential role in GSD and central obesity (JMJD1C-regulated lipid synthesis)." (PMID 38529389, 2024).
cholesteatoma (1 paper, 2015). A pathologic process characterized by the proliferation of keratinizing squamous epithelium resulting in the accumulation of keratin and cells in the middle ear and/or mastoid. "We found epidermal fatty acid binding protein (FABP5) is highly overabundant in cholesteatoma compared to normal mucosa (4.3-fold), with a lesser increase compared to skin." (PMID 26608071, 2015).
chronic lung disease (1 paper, 2009). According to the definitions of the American and British Thoracic Societies, including pulmonary functional tests, X-rays, and CT scans for items such as fibrosis, bronchiectasis, bullae, emphysema, nodular or lymphomatous abnormalities. "Further studies such as knockdown or overexpression experiments in human airway epithelial cells should be completed to help us further understand FABP-5's roles in the human innate immune response in COPD and other chronic lung diseases presenting persistent airway bacterial infections." (PMID 19718433, 2009).
chronic obstructive pulmonary disease (1 paper, 2019). A chronic and progressive lung disorder characterized by the loss of elasticity of the bronchial tree and the air sacs, destruction of the air sacs wall, thickening of the bronchial wall, and mucous accumulation in the bronchial tree. "A previous study indicated that Fabp5 was downregulated in the airway epithelial cells of smokers with chronic obstructive pulmonary disease." (PMID 30770755, 2019).
colitis (1 paper, 2025). Inflammation of the colon. "Preclinical:: FABP5 inhibitor, PPARγ agonists ameliorate colitis.Clinical:: T cell lipid raft abnormalities in CD; Enhancing FAO reverses pathogenic Trm cells." (PMID 41280910, 2025).
colon adenocarcinoma (1 paper, 2025). "We first compared the expression of five CRBPs—retinol‐binding protein 1 and 2 (RBP1/2), CRABP1, CRABP2, and FABP5—in normal (N) versus tumor (T) tissues in The Cancer Genome Atlas (TCGA)‐Colon Adenocarcinoma (COAD) dataset." (PMID 40305785, 2025).
diabetic cardiomyopathy (1 paper, 2020). Diabetic cardiomyopathy is a disorder of the heart muscle in people with diabetes. "We studied whether reduced FA uptake in the heart is protective against streptozotocin (STZ)-induced diabetic cardiomyopathy by using mice doubly deficient in fatty acid binding protein 4 (FABP4) and FABP5 (DKO mice)." (PMID 33257783, 2020).
dystrophinopathy (1 paper, 2018). "Although this excludes the dystrophinopathy-associated change in liver FABP5 as a robust and highly specific biomarker of X-linked muscular dystrophy, altered FABP5 levels may nevertheless be useful as a general pathophysiological marker in conjunction with other disease indicators." (PMID 30386187, 2018).
esophageal tumor (1 paper, 2016). "As a result, we speculated that CRABP2 acted as a tumor suppressor in esophageal tumor tissues due to the high CRABP2/FABP5 ratio." (PMID 26839961, 2016).
extramammary Paget disease (1 paper, 2024). A malignant neoplasm in which there is infiltration of the skin by neoplastic large cells with abundant pale cytoplasm and large nuclei with prominent nucleoli (Paget cells). "Within extramammary Paget’s disease tumor tissues, FABP5 exhibits co-localization with CK7, CK20, and EMA, accompanied by substantial expression levels." (PMID 38596682, 2024).
Follicular Cyst (1 paper, 2023). Cyst due to the occlusion of the duct of a follicle or small gland. "FGF7 regulated the PPAR signaling pathway (FABP5 and SCD) and the MAPK signaling pathway (FGF1, FGFR2, IL1A, TGFB1, and CSF1) and pathways in cancer (IL7, CD44, SMAD2, and MMP2) may be involved in the formation of follicular cysts." (PMID 38274662, 2023).
folliculitis (1 paper, 2026). Inflammation of the hair follicles. "Finally, we demonstrated that an AP-1 inhibitor, T-5224, downregulates FABP5 in human keratinocytes and reduces pustule formation in a mouse model of high-fat diet-induced folliculitis." (PMID 41657309, 2026).
gastric tumor (1 paper, 2022). "PD-L1 blockade decreases FABP4 and FABP5 expression in gastric tumor cells, while increases FABP4 and FABP5 expression in Trm cells, enhancing fatty acid uptake by Trm cells and sustaining survival of Trm cells." (PMID 35899119, 2022).
H1N1 influenza A virus infection (1 paper, 2019). "The anti inflammatory role of fatty acid binding protein 5 (FABP5) in H1N1 influenza A virus infection has been demonstrated using FABP5−/− mice." (PMID 30871179, 2019).
hyperlipidemia (1 paper, 2023). "In vivo immunohistochemical analysis demonstrated higher Fabp5 expression in the hyperlipidemia-associated AP group compared to the AP and control groups." (PMID 38188879, 2023).
infarction (1 paper, 2026). A localised pathological necrosis of tissue resulting from obstruction of the blood supply usually by a thrombus, an embolus, or vascular torsion. "Modulating FABP5 expression level may influence post-infarction neuronal recovery." (PMID 41907041, 2026).
invasive breast carcinoma (1 paper, 2025). A carcinoma that infiltrates the breast parenchyma. "To further investigate the role of FABP5 in invasive breast cancer, we first analyzed the correlation between FABP5 expression in tumor cells and various clinical parameters, including age, BMI, tumor size, tumor Elston-Ellis grade, metastasis and patient vital status." (PMID 40106183, 2025).
ischemia (1 paper, 2021). A hypoperfusion of the BLOOD through an organ or tissue caused by a PATHOLOGIC CONSTRICTION or obstruction of its BLOOD VESSELS, or an absence of BLOOD CIRCULATION. "In contrast, FABP5 expression is elevated in CA1 neurons (which are apoptotic after ischemia), but was unchanged in DG neurons that remained relatively stable after ischemia in the hippocampus of adult monkeys, suggesting that FABP5 is likely involved in the survival of hippocampal neurons." (PMID 34068550, 2021). "Moreover, co-staining FABPs in different cell types in the cortical area of the penumbra suggests that increased FABP3, FABP5 and FABP7 expression occurred only in specific cells expressing these proteins before ischemia." (PMID 34068550, 2021). "AA is known to elevate in during ischemia and it is also a strong ligand of FABP3 and FABP5." (PMID 34068550, 2021). "However, it is unclear whether one FABP or FABP3, FABP5 and FABP7 collectively induced mPGES-1 after ischemia." (PMID 34068550, 2021).
keratosis pilaris (1 paper, 2024). A form of dry skin characterized by hair follicles plugged by scale. "Proteomic profiling revealed heightened expression of KRT6C and FABP5 in arsenic-induced keratosis pilaris." (PMID 38596682, 2024).
kidney cancer (1 paper, 2024). Primary or metastatic malignant neoplasm involving the kidney. "Previous studies have demonstrated that increased FABP5 expression in kidney cancer tissues leads to shorter OS in patients, and that when FABP5 is knocked out, the proliferative ability of tumor cells is reduced." (PMID 38361759, 2024).
lentivirus infection (1 paper, 2021). Virus diseases caused by the Lentivirus genus. "Results of qRT‐PCR and western blot assays indicated that FABP5 was significantly up‐regulated after lentivirus infection." (PMID 33837625, 2021).
leukemia (1 paper, 2022). A malignant (clonal) hematologic disorder, involving hematopoietic stem cells and characterized by the presence of primitive or atypical myeloid or lymphoid cells in the bone marrow and the blood. "The increased expression of Fabp5 also raises the possibility that DKO and E2a-/- leukemias may have different metabolic requirements." (PMID 35371057, 2022).
Lewy body diseases (1 paper, 2023). "The intricate involvement of FABPs, particularly FABP3, FABP5, and FABP7, in the pathogenesis of Lewy body diseases highlights their significance in reflecting the disease state." (PMID 37686075, 2023).
lipid metabolism disorders (1 paper, 2024). "Overexpression of ALKBH5 increases FABP5 expression in a m6A-IGF2BP2 dependent manner, leading to lipid metabolism disorders.The research report that inhibition of ALKBH5 could promote m6A modification of CCL28 mRNA and increase its stability." (PMID 38918701, 2024).
malaria (1 paper, 2021). Malaria is a serious and sometimes fatal disease caused by a parasite that commonly infects a certain type of mosquito which feeds on humans. "Among nine key genes, four genes (SAMSN1, SLC39A8, SMPDL3A, and FABP5) were positively correlated with malaria severity and upregulated in CM." (PMID 33942992, 2021). "SAMSN1, SLC39A8, SMPDL3A, and FABP5 were positively correlated with malaria phenotype/severity and showed an upregulation in the CM group compared with healthy controls, while MBP, SPSB3, PSMF1, SHARPIN, EIF3B were negatively correlated with malaria severity and downregulated in the DEG." (PMID 33942992, 2021). "Within the nine genes, five genes (MBP, SAMSN1, PSMF1, SLC39A8, and EIF3B) were previously found to be involved in malaria, and the remaining four genes (SMPDL3A, FABP5, SPSB3, and SHARPIN) were identified for the first time in the current study." (PMID 33942992, 2021).
malignant glioma (1 paper, 2021). A grade III or grade IV glioma arising from the central nervous system. "In malignant gliomas, the median ratio of FABP5/CRABP2 mRNA expression of 3.6 in short-term survivors (≤6 months) was significantly higher than that of long-term survivors (≥36 months) of 1.4, indicating that the FABP5/CRABP2 ratio can determine the direction of cell differentiation." (PMID 34632074, 2021).
meningioma (1 paper, 2013). A generally slow growing tumor attached to the dura mater. "Fatty acid binding protein 5 (FABP5) shows also increased expression for both benignB and atypical meningioma subgroups with respect benignA meningioma." (PMID 23840654, 2013).